NRDE2 (NRDE-2, necessary for RNA interference, domain containing)
Description:
Protein of the nuclear speckles that regulates RNA degradation and export from the nucleus through its interaction with MTREX an essential factor directing various RNAs to exosomal degradation. Changes the conformation of MTREX, precluding its association with the nuclear exosome and interaction with proteins required for its function in RNA exosomal degradation. Negatively regulates, for instance, the degradation of mRNAs and lncRNAs by inhibiting their MTREX-mediated recruitment to nuclear exosome. By preventing the degradation of RNAs in the nucleus, it promotes their export to the cytoplasm. U5 snRNP-associated RNA splicing factor which is required for efficient splicing of CEP131 pre-mRNA and plays an important role in centrosome maturation, integrity and function during mitosis. Suppresses intron retention in a subset of pre-mRNAs containing short, GC-rich introns with relatively weak 5' and 3' splice sites. Plays a role in DNA damage response.
Synonyms: C14orf102; FLJ14051
Tractability: Small molecule: a structure with a bound ligand is known. PROTAC: ubiquitination databases record sites on it; its protein half-life has been measured.
Gene: Protein-coding gene on chromosome 14 (90,267,860 to 90,331,981, reverse strand). Ensembl gene ENSG00000119720.
Subcellular location: Nucleus speckle; Nucleus, nucleolus; Nucleus, nucleoplasm; Nucleus
Subcellular location (Human Protein Atlas): Mitochondria; Nucleoplasm
Gene Ontology:
Molecular function: protein binding
Biological process: DNA damage response; mitotic cell cycle; mRNA stabilization; positive regulation of RNA export from nucleus; RNA splicing; negative regulation of RNA catabolic process; regulatory ncRNA-mediated heterochromatin formation
Cellular component: mitochondrion; nuclear speck; nucleolus; nucleoplasm; nucleus
Genetic constraint (gnomAD): Loss-of-function variants: 67 observed, 117.9 expected, observed/expected ratio (o/e) 0.57, 90% interval 0.47 to 0.7. The upper end of that interval is the gene's LOEUF score, 0.7, which puts it in group 2 of 6, group 1 being the genes least tolerant of losing a copy. Missense variants: 1,274 observed, 1,449.7 expected, observed/expected ratio (o/e) 0.88, 90% interval 0.84 to 0.92. Synonymous variants: 481 observed, 546.54 expected, observed/expected ratio (o/e) 0.88, 90% interval 0.82 to 0.95.
Homologues: Orthologues: chimpanzee NRDE2 (99% identical), pig NRDE2 (88% identical), guinea pig NRDE2 (85% identical), dog NRDE2 (84% identical), rabbit NRDE2 (81% identical), rat Nrde2 (81% identical), mouse Nrde2 (81% identical), tropical clawed frog nrde2 (55% identical), zebrafish nrde2 (49% identical), Caenorhabditis elegans nrde-2 (18% identical), Drosophila melanogaster CG5877 (17% identical).
Diseases named in the same sentence as NRDE2 in open-access papers:
NRDE2 is named in the same sentence as 4 diseases in open-access papers, as found by Europe PMC text mining. Sharing a sentence is not in itself a finding about the gene and the disease. The quoted sentences say what the papers report.
cancer (1 paper, 2015). A tumor composed of atypical neoplastic, often pleomorphic cells that invade other tissues. "As a result of this testing the two of these SNPs rs7894051 (in ECHS1 gene), and rs4904670 (in NRDE2 gene) were selected for further analyses of their associations with major diseases (cancer and CHD) and physiological aging changes." (PMID 25918517, 2015).
NRDE2 also shares sentences with these, for which no sentence is quoted: brain cancer (1 paper); melanoma (1); schizophrenia (1).